TLR2 (toll like receptor 2)
Diseases named in the same sentence as TLR2 in open-access papers (continued):
Sharing a sentence is not in itself a finding about the gene and the disease.
hidradenitis suppurativa (2 papers, 2022 to 2024). A chronic suppurative and cicatricial disease of the apocrine glands occurring chiefly in the axillae in women and in the groin and anal regions in men. "Variants involved the TLR2 and MPO genes in the first family and the MMP2, GJB2, and TLR4 genes, some of which have already been previously reported as possible candidates for hidradenitis suppurativa." (PMID 39595064, 2024). "has been demonstrated to trigger the T helper 17 (Th17) immune responses and activate Toll-like receptor 2 (TLR-2), leading to an increased production of IL-1 and IL-23, which are involved in the pathogenesis of hidradenitis suppurativa." (PMID 36232581, 2022).
hyperandrogenemia (2 papers, 2025). "Previous research has linked TLR2 with polycystic ovary syndrome and metabolic comorbidities in obese women, with TLR2 mRNA levels increasing from early to mid-luteal phase." (PMID 40564256, 2025).
Hyperbilirubinemia (2 papers, 2017 to 2023). An increased amount of bilirubin in the blood. "It has been shown that in UGT1A1 knocked-out mice, Toll-like receptor 2 (TLR2) is required for regulating gliosis, pro-inflammatory mediators, and oxidative stress when neonatal mice are exposed to severe hyperbilirubinemia, but TLR2 also has anti-apoptotic properties." (PMID 37759499, 2023). "Moreover, the involvement of glia and the role of TLR2 were shown in the humanized knockout mouse model of hyperbilirubinemia, although the time course of the disease onset was not investigated." (PMID 28340583, 2017).
hyperplastic polyp (2 papers, 2010 to 2020). A polyp found mainly in the stomach and colon. "The expression levels of TLR2, 3, 4, and 5 were analyzed in intestinal biopsy specimens of 21 hyperplastic polyp (HP), 16 sessile serrated adenoma (SSA), 29 tubular adenoma (TA), 21 villous/tubulovillous (VP/TVP) cases, and 31 normal controls." (PMID 33255933, 2020). "In summary, airway SPLUNC1 production is up-regulated following bacterial (i.e., Mp) infection and TLR2 agonist stimulation." (PMID 21054862, 2010).
idiopathic pulmonary arterial hypertension (2 papers, 2018 to 2021). A sporadic form of pulmonary arterial hypertension (PAH) characterized by elevated pulmonary arterial resistance leading to right heart failure. "Increased PWV resulting from large arterial stiffening has been associated with proinflammatory responses (increased TLR2, NF-kB activation) in pulmonary arterial ECs in vitro and in intralobar pulmonary arterial ECs from humans with idiopathic pulmonary arterial hypertension." (PMID 34594238, 2021). "TLR signaling, especially involving TLR2 and 4, has been described in human pulmonary vascular cells and patients with idiopathic pulmonary arterial hypertension." (PMID 29560100, 2018).
IgA nephropathy (2 papers, 2009 to 2020). "Loss of apical TLR2 staining in tubuli in later phases of UUO or during severe forms of IgA nephropathy could reflect loss of apical brush border due to tubular damage." (PMID 19479087, 2009). "In this study we characterized the expression pattern of TLR2 in kidneys from patients with obstructive hydronephrosis, severe IgA nephropathy as well as from mice subjected to obstructive nephropathy." (PMID 19479087, 2009). "In agreement, we found that patients with severe IgA nephropathy had a predominant interstitial TLR2 expression with occasionally apical staining of tubuli." (PMID 19479087, 2009). "Similar to patients with hydronephrosis we found a strong increase of TLR2 expression in all the fifteen analyzed kidneys of IgA nephropathy patients compared to control renal biopsy specimens." (PMID 19479087, 2009). "TLR2 positive interstitial cells in IgA nephropathy patients and mice subjected to UUO therefore most likely reflect the influx of leukocytes known to express TLRs and the accumulation of myofibroblasts." (PMID 19479087, 2009). "Furthermore, the expression of TLR2, 3, 5, and 9 correlated with proteinuria levels in patients with IgA nephropathy." (PMID 32079183, 2020). "Indeed, we found numerous TLR2-positive macrophages in patients with IgA nephropathy." (PMID 19479087, 2009).
immunotoxicity (2 papers, 2023 to 2025). "Similarly, RES exerted its antioxidant properties by regulating the Nrf2 and TLR2-Myd88-NF-κB signaling pathways that significantly attenuated the liver immunotoxicity in H2O2-treated tilapia." (PMID 37168854, 2023). "The roles of TLR2 and TLR4, as well as the NF-κB pathway, in mediating immunotoxicity to PBBs and their transformations need to be further investigated." (PMID 40278609, 2025).
inflammatory skin disease (2 papers, 2021). Inflammatory skin disorders covers a broad category that includes many conditions ranging in severity, from mild itching to grave medical health complications These disorders are common in people of all ages and races. "When activated macrophages are affected by UVB-irradiated keratinocytes, they activate the TLR2 and TLR4 pathways and cause inflammatory skin diseases." (PMID 33670841, 2021). "In the present study, we aimed to investigate how TLR2 is related to inflammatory skin diseases and whether it can be used as a therapeutic target." (PMID 35011650, 2021).
interstitial lung disease (2 papers, 2014 to 2020). A diverse group of lung diseases that affect the lung parenchyma. "Subjects with nailfold capillaroscopy abnormalities had a higher amount of TLR2+ classical and non-classical monocytes and those with interstitial lung disease (ILD) had a higher percentage of TLR4+ non-classical monocytes." (PMID 32164729, 2020).
intestinal tumor (2 papers, 2010 to 2017). "Previous studies have shown that TLR signaling and the common adaptor molecule MyD88 are critically involved in intestinal epithelial cell homeostasis and the development of intestinal tumors, yet the role of TLR2 has not been extensively studied." (PMID 20885960, 2010). "Despite the evident roles of TLR2 in IEC homeostasis and enhancement of tolerance in the lamina propria microenvironment, no study has elucidated the role that TLR2 might play in transformation of intestinal epithelial cells leading to intestinal tumors." (PMID 20885960, 2010).
irritable bowel syndrome (2 papers, 2023 to 2025). Irritable bowel syndrome (IBS) is a chronic functional condition of the lower gastrointestinal (GI) tract characterized by abdominal pain or discomfort and disordered bowel habit (diarrhea, constipation, or fluctuation between the two). "G allele Toll-like receptor-2 gene Arg753Gln (rs5743708) and AA genotype interleukin-10 gene-1082A/G (rs1800896) polymorphisms can be the marker of the emergence of adenomatous polyps of the colon concomitant with irritable bowel syndrome." (PMID 37404119, 2023).
keloid (2 papers, 2024). An irregularly shaped, elevated mark on the skin caused by deposits of excessive amounts of collagen during wound healing. "Among the genes induced in keloids are Tlr1, Tlr2, Tlr6, and Acod1, commonly up-regulated by bacteria." (PMID 39081787, 2024).
kidney failure (2 papers, 2017 to 2020). An acute or chronic condition that is characterized by the inability of the kidneys to adequately filter the blood. "Eight genes related to kidney toxicity, including kidney failure (CASP1, FCGR2A, FCGR2B, TLR2, TLR4, P = 0.003), damage of renal tubule (TLR2, TLR4, P = 0.01), proximal tubular toxicity (CTSS, LYZ, SLC22A5, P = 0.007) and their expression across 6 datasets were not confounded by tissue types." (PMID 28051114, 2017). "The expressions of TLR2 and TLR4 remarkably increased in nephrotic diabetic patients with or without kidney failure and in non-diabetic nephrotic patients (with kidney failure) in comparison with normal subjects." (PMID 33442388, 2020). "The higher expression of TLR2 and TLR4 in nephrotic diabetic patients with kidney failure than in nephrotic diabetic patients without kidney failure reflects their important roles in the progress of DNP to reach the end disease state subjected to HD." (PMID 33442388, 2020). "Therefore, this study was conducted to scrutinize the patterns of changes and roles of TLR2 and TLR4 expressions in relation to proinflammatory Th1 cytokine levels and INS resistance in nephrotic diabetic patients with or without kidney failure." (PMID 33442388, 2020).
left ventricular hypertrophy (2 papers, 2015 to 2016). Enlargement of the LEFT VENTRICLE of the heart. "The decrease of the inflammatory response upon TLR2 and -9 ligand challenge in TAC Tlr4-/- mice demonstrates that a lack of TLR4 signaling does not only prevent left ventricular hypertrophy but also protects the mice from a cardiac stress induced hyperinflammatory reaction." (PMID 26588247, 2015).
lepromatous leprosy (2 papers, 2015 to 2024). A chronic communicable infection which is a principal or polar form of leprosy. "(2003) identified that TLR1 and TLR2 are expressed in greater amounts in individuals with tuberculoid leprosy than in patients with lepromatous leprosy." (PMID 39308868, 2024).
leukopenia (2 papers, 2011 to 2015). "It is worth mentioning that the deletion of the TLR2, TLR9 or MyD88 genes did not seem to affect the irinotecan-induced cytotoxic effects because the leukopenia was still observed." (PMID 26440613, 2015).
lipid metabolic disorders (2 papers, 2016 to 2025). "The expression of TLR2 was required for EPS to improve the lipid metabolic disorders." (PMID 27786292, 2016). "For example, red mold rice significantly reduced cholesterol, LDL, and arterial plaque through TLR2 and TLR4 pathways, while monascin alleviated lipid metabolism disorders by modulating key gene expressions and enhancing beneficial bacterial populations." (PMID 40002095, 2025).
lymphedema (2 papers, 2009 to 2025). Excess fluid collection in tissues, causing swelling. "BmA also induced significantly higher expression of TLR2, 4, 7, and 9 as well Nod1 and 2 mRNA in patients with lymphedema compared with asymptomatic controls." (PMID 19381284, 2009). "Our data reveal that modulation of TLR expression is an important feature of chronic lymphatic pathology since patients with lymphedema exhibit significantly enhanced expression of TLR2, 4, 7 and 9 mRNA in comparison to asymptomatic, infected patients." (PMID 19381284, 2009).
male infertility (2 papers, 2016 to 2022). The inability of the male to effect fertilization of an ovum after a specified period of unprotected intercourse. "In addition, cytokines mediate male infertility by impairing sperm motility and repressing testosterone synthesis through the activation of Toll-like receptors-2 and 4 (TLR-2 and TLR-4) located on the human spermatozoa membrane." (PMID 36303638, 2022).
memory impairment (2 papers, 2021 to 2022). "One study showed, injection of αSynOs in the brain ventricles of wild type mice caused memory impairment through a TLR-2 dependent mechanism, which is closely associated with activation of glial cells in the hippocampus; and contrary to AβOs, TLR-4 was not involved in memory impairment." (PMID 35885050, 2022). "The results suggested that xanthoceraside inhibited the TLR2 pathway and downregulated MAPK and NF-κB activity, which may be associated with improved learning and memory impairment." (PMID 34526898, 2021).
mesothelioma (2 papers, 2021 to 2022). A usually malignant and aggressive neoplasm of the mesothelium which is often associated with exposure to asbestos. "In contrast, neither TLR4 nor TLR2 stimulation with LPS and bacterial peptidoglycan, respectively, could prevent mesothelioma development (p = 0.62 and 0.91, respectively)." (PMID 36714124, 2022).
migraine (2 papers, 2022 to 2024). "Several studies have shown further evidence that both mast cells and T cells are activated and the expression of chemokine and TLR2 are increased in migraines." (PMID 35987639, 2022). "Although the relationship between TLR4 and migraine is more well-studied than that between TLR2 and TLR3, the related upstream and downstream mechanisms still require significant research." (PMID 35987639, 2022). "To date, several studies have shown that TLR2, TLR3, and TLR4 are associated with migraine." (PMID 35987639, 2022). "However, the mechanism of TLR2 pathway during migraine attacks remains unclear." (PMID 35987639, 2022). "It is not difficult to see that research on TLR2 and migraine is still in its infancy." (PMID 35987639, 2022).
monocytic leukaemia (2 papers, 2013 to 2022). "Similarly, PGN-mediated activation of TLR2 and other pathways has been shown to enhance expression of chemoattractant genes in human monocytic leukaemia cells." (PMID 23460923, 2013).
mucormycosis (2 papers, 2015 to 2021). "Compared to hematological controls, individuals with IA and mucormycosis had defective expression of dectin-1; in addition, patients with mucormycosis had decreased TLR2 and increased TLR4 expression." (PMID 25835547, 2015).
multiple system atrophy (2 papers, 2018 to 2025). Multiple system atrophy (MSA) is a neurodegenerative disorder characterized by autonomic failure (cardiovascular and/or urinary), parkinsonism, cerebellar impairment and corticospinal signs with a median survival of 6-9 years. "Regarding PRRs, such as TLR4 and TLR2, have been demonstrated that are able to bind to α-synuclein in multiple system atrophy (MSA) models, where the overexpression of α-synuclein increases motor impairment as well as dopaminergic degeneration in the SNpc." (PMID 30618635, 2018).
myositis (2 papers, 2020 to 2023). "The murine models of myositis have demonstrated the importance of TLR2 and TLR4 in the induction of disease in IIM, since the deficiency of both TLRs or their signaling protein MyD88 completely abolish the disease phenotype." (PMID 32164729, 2020). "Although antigen-specific T cell proliferation and production of class-switched autoantibodies suggest a role for adaptive immunity in this model, the development of myositis is absolutely dependent on MyD88, with substantial (but overlapping) contributions from TLR2 and TLR4 signaling." (PMID 37809058, 2023).
non-alcoholic fatty liver disease (2 papers, 2011 to 2025). "TLR-2 deficiency appears to play a protective role in induction of nonalcoholic fatty liver disease and probably modify TLR-4 signaling." (PMID 22114589, 2011). "It appears that TLR-2 deficiency protects from nonalcoholic fatty liver disease and probably modifies the signaling pathway of TLR-4." (PMID 22114589, 2011). "For example, P.g can accumulate in the liver, where its fimbrial protein FimA binds to Toll-like receptor 2 (TLR2), complement receptor 3 (CR3), and CXC-chemokine receptor 4 (CXCR4), triggering various immune responses that promote the development of non-alcoholic fatty liver disease(NAFLD)." (PMID 40792109, 2025).
oral disease (2 papers, 2020 to 2024). "The association of SNPs in TLR2 and TLR4 genes with different infectious diseases (including oral diseases) was examined." (PMID 39000094, 2024). "However, on the other hand, how induction of TLR2/4 in oral disease affects the expression and function of miR-146a may need further investigation." (PMID 32291538, 2020).
ovarian tumor (2 papers, 2013 to 2023). "Versican V1 produced by ovarian tumor cell leads to activation of TLR2 and its coreceptors TLR6 and CD14 in macrophages." (PMID 23424670, 2013). "In summary, we have found that versican V1 enhances hCAP18/LL-37 expression in macrophages through activation of TLR2 and subsequent vitamin D-dependent mechanisms which promote ovarian tumor progression in vitro." (PMID 23424670, 2013). "Based on the limited number of cancer studies on TLR1 and TLR2, it appears that their modulation is cancer-type dependent, with a pro-tumoral role in CRC, gastric and ovarian tumors and an anti-tumoral role in melanoma and lung cancer." (PMID 37112730, 2023). "The expression of functional TLR2 is found in epithelial cells, but it is also expressed in colorectal (CRC), gastric and ovarian tumors." (PMID 37112730, 2023).
Pain (2 papers, 2012 to 2023). An unpleasant sensory and emotional experience associated with actual or potential tissue damage, or described in terms of such damage. "In this study, we discovered that GT1b, a previously identified endogenous TLR2 agonist used in nerve-injury-induced neuropathic pain, induces sexually dimorphic central pain sensitization; it induced pain sensitization only in male but not in female mice." (PMID 36899944, 2023). "Moreover, our recent study showed that TLR2 expression were also elevated in spinal cord in CIP rats (data not shown), indicating a possible role of TLR2 and even other TLRs in cancer induced pain similar to what has been observed in neuropathic pain." (PMID 22607655, 2012).
pancreatitis (2 papers, 2016 to 2021). Inflammation of the pancreas. "In the present study, the expression levels of the TLR2 gene were 10.63- and 7.62-fold higher in the pancreatitis-associated DHAV-1 and classical-type DHAV-1 infection groups, respectively, than in the control group, indicating that TLR2 may be involved in the host response to DHAV infection." (PMID 34482448, 2021).
papillary thyroid cancer (2 papers, 2019 to 2022). "Our analysis concludes that TIMP1, LOX, CD276, IFNA1, TLR2, and POSTN are identified as thyroid cancer biomarkers, which lead to the different clinical courses of a woman older than 55 years old with papillary thyroid cancer." (PMID 36120433, 2022). "TIMP1, LOX, CD276, IFNA1, TLR2, and POSTN have different expressions in PTCs, which lead to the various clinical courses of a woman older than 55 years old with papillary thyroid cancer." (PMID 36120433, 2022). "According to the ROC results, TIMP1, LOX, CD276, IFNA1, TLR2, and POSTN were considered to play a more critical role in malignant papillary thyroid cancer or immature cancer of papillary thyroid cancer." (PMID 36120433, 2022).
parasite (2 papers, 2018 to 2020). "TLR2 mediates cell activation by the recognition of microorganisms and microbial products, and also is involved in the defense and elimination of parasites infection, including Plasmodium falciparum, Toxoplasma gondii, and Trypanosoma cruzi." (PMID 29692771, 2018).
Peptic ulcer (2 papers, 2021 to 2025). The term peptic ulcer refers to acid peptic injury of the digestive tract, resulting in mucosal break reaching the submucosa. "Previously, in patients with clear evidence of peptic ulcers, H. pylori infection showed a significant increase in TLR2 and TLR4 mRNA expression in the antral region compared to uninfected samples." (PMID 40362298, 2025). "In studies in Iran and in Turkey, patients carrying the TLR2 rs3804099 CT genotype more frequently had peptic ulcers and H. pylori infection than healthy individuals." (PMID 34322122, 2021).